AFP (alpha fetoprotein)
Diseases named in the same sentence as AFP in open-access papers (continued):
Sharing a sentence is not in itself a finding about the gene and the disease.
tumor (continued). "A Cox regression analysis showed that age, sex, AFP, grade, stage, tumor size, surgery, and chemotherapy were independent risk factors." (PMID 38001570, 2023). "High Ki67 expression was significantly associated with AFP ≥ 400 ng/mL (P = 0.015), tumor size ≥ 5 cm (P = 0.012), incomplete tumor capsule (P < 0.001), MVI (P = 0.001), PVTT (P = 0.003), advanced BCLC stage (P = 0.01), and VCE (P = 0.001)." (PMID 36600214, 2023). "The results showed that CDCA8 levels were significantly positively associated with AFP levels (p = 0.003), tumor number (p = 0.007), and vascular invasion (p = 0.045)." (PMID 36639822, 2023). "Male gender, increasing numbers of tumors, bilobar distribution, larger tumor size, and increasing AFP are associated with increased discordance." (PMID 37326440, 2023). "According to the present study, the AFP value and total tumor size are independent risk factors for HCC recurrence after LT, consistent with previous research." (PMID 37909200, 2023). "Several risk factors, including tumor size, tumor number, serum alpha-fetoprotein level, and peritumoral enhancement, have been reported as being related to MVI in HCC." (PMID 36836479, 2023). "For the existing standard, the AFP model can effectively identify low-risk recurrence HCC patients with multiple tumor nodules." (PMID 36967432, 2023). "The progressively established differential systems, starting with the French: point values for tumor size, 0, 1, 4, and AFP levels, 0, 2, 3, to correlate risk assessment." (PMID 38001597, 2023). "The result demonstrated that higher risk scores significantly corresponded to advanced tumour stage, younger age and higher AFP level." (PMID 36919714, 2023). "Our multicentre, large-cohort study elucidates that elevated preoperative levels of CRP and AFP are significantly associated with the more aggressive biological tumor behavior and inferior prognosis following hepatectomy." (PMID 38053048, 2023). "In hepatitis B virus (HBV)-related HCC, IgG immunopositivity in tumour samples was associated with higher levels of core-fucosylated AFP, larger tumours, and higher prevalence of portal vein invasion." (PMID 37027398, 2023). "MVFC‐identified tumor mutations combined with AFP showed the best prognostic efficiency than either of the two biomarkers." (PMID 37496285, 2023). "In the group with an initial AFP level > 100 ng/mL, a prediction of complete tumor necrosis based on ΔAFP was associated with an AUC of 0.717 (95% confidence intervals 0.546–0.887, p = 0.013) and an optimal cut-off of ≥340.5 ng/mL." (PMID 37568778, 2023). "They suggested tumor characteristics such as tumor size > 5 cm, AFP > 400 μg/mL, and microvascular invasion as risk factors of early-stage recurrence." (PMID 37345066, 2023). "Recent evidence showed that a high level of AFP at baseline is also significantly associated with early tumor recurrence and poor prognosis of HCC in different clinical settings, such as after liver resection or liver transplantation." (PMID 36766518, 2023). "Tumor markers associated with gastrointestinal malignancies, such as alpha-fetoprotein, carcinoembryonic antigen, and carbohydrate antigen, are usually within the normal range, as PHL primarily arises from lymphoid cells rather than epithelial cells." (PMID 38115256, 2023). "Large tumour size (p = 0.000) and high AFP levels (0.012) were independently associated with PVT in HCC patients with preserved liver function." (PMID 37533945, 2023). "Multivariate analysis in this study showed that the main factors associated with OS were PVTT type, tumor number, AFP, and treatment, which was the same as those observed in the previous study." (PMID 36920551, 2023). "In the subgroup with an AFP < 100 ng/mL, a prediction of complete tumor necrosis based on ΔAFP was associated with an AUC of 0.604 (95% confidence intervals 0.452 to 0.756, p = 0.180) and an optimal cut-off of ≥10.2 ng/mL." (PMID 37568778, 2023).
tumor (continued). "Elevated CDCA8 expression in HCC patients was markedly associated with T stage, pathological status (PS), tumor status (TS), histologic grade (HG), and AFP." (PMID 36855818, 2023). "Multivariate Cox regression analysis showed that differentiation, tumor size, AFP and fibrosis were independently association with the prognosis of HCC patients after partial hepatectomy." (PMID 36717904, 2023). "Other studies reported that [18F]FDG PET/CT parameters showed positive associations with tumor markers such as AFP and HCG12,13." (PMID 37848723, 2023). "Immunohistochemical expression of diagnostic markers EMA, vimentin, NSE and CD99, and AFP was comparable to the expression observed in the primary tumor." (PMID 38201285, 2023). "To explore the CRGs risk model with clinical characteristics, we found that the CRGs signature was associated with multiple clinical features, including alpha-fetoprotein, histological grade, tumor stage, as well as TCGA molecular subtypes, etc.." (PMID 36843949, 2023). "High level of serum AFP has been shown to help to diagnose patients with bone metastases with diagnostic accuracy of 75% as well as to predict tumor size, location, risk of metastases, and duration of treatment." (PMID 37404755, 2023). "Pre-operative alanine aminotransferase (ALT), aspartate aminotransferase (AST), total bilirubin, AFP, tumor number, BCLC stage, SII, and ALBI were all linked with favorable post-operative outcomes (P < .05)." (PMID 36620927, 2023). "Studies showed that the serum level of AFP in patients with non-small cell lung cancer can be utilized to predict location-based tumor susceptibility and duration of location-based tumor treatment." (PMID 37404755, 2023). "In summary, we demonstrated that by combining CTC status and AFP levels ≥ 400 ng/ml, a group of patients at high risk of postoperative tumor recurrence was prospectively identified." (PMID 38012205, 2023). "The models were established based on gender, ALBI grade, serum AFP level, tumor volume and number, and divided HCC recurrence risk into low, medium and high." (PMID 37369911, 2023). "Postoperative recurrence of HCC is associated with several major prognostic factors such as tumor size, number of nodules, vascular invasion, tumor encapsulation, blood transfusion, high α-fetoprotein (AFP) levels, and resection margin status." (PMID 36980321, 2023). "As a specific marker of HCC, AFP was closely linked with tumor progression and survival of HCC patients." (PMID 36675418, 2023). "One patient (2.4 percent) had high levels of alpha-fetoprotein (AFP), a tumor marker linked to liver and testicular malignancies." (PMID 35774682, 2022). "Cases with this variant had high serum AFP levels, large tumor sizes, and frequent LVI and were diagnosed at later stages." (PMID 36117166, 2022). "Surveillance can be optimally performed by estimating individual recurrence risk through established risk scores that typically include type of tumor treatment, pathological analysis (in the case of resection and LT), and biomarkers (e.g. AFP)." (PMID 35142988, 2022). "Multiple logistic regression analysis identified tumor margin, direct bilirubin, maximum tumor diameter, and AFP as independent risk factors associated with the risk of MVI." (PMID 36577952, 2022). "SHC4 was overexpressed in HCC compared to adjacent normal liver tissues and increased SHC4 expression was associated with high AFP level, incomplete tumor encapsulation, poor tumor differentiation and poor prognosis." (PMID 35033067, 2022). "The individual risk score is related to AFP level, tumor vascular invasion, and histological grade, and this also reflects the risk score is related to the tumor recurrence possibility." (PMID 35047095, 2022). "Multivariate analysis showed that marital status, grade, AFP, vascular invasion, tumor size, and number of lesions were independent risk factors for 5-year CSD of patients." (PMID 36451200, 2022).
tumor (continued). "In the training cohort, maximum tumor diameter (> 50 mm), tumor margin, direct bilirubin (> 2.7 μmol/L), and AFP (> 360.7 ng/mL) were confirmed as independent risk factors for MVI." (PMID 36577952, 2022). "Elevated ɣ-GGT levels are associated with vascular invasion, tumour size, number of tumours and AFP levels 26-28." (PMID 35399712, 2022). "There were 35 cases (45%) where tumor markers were above the diagnostic threshold (HCG > 100 IU/L or AFP > 10 ng/mL) and upfront resection was performed." (PMID 35205726, 2022). "In this study, we found that tumor size, vascular invasion, AFP level, and number of lesions were independent risk factors for 5-year CSD through univariate and multivariate logistic regression analysis." (PMID 36451200, 2022). "The preoperative risk factors associated with ER were age, alpha-fetoprotein, tumor diameter, and tumor number, and the postoperative risk factors associated with ER were age, tumor diameter, tumor number, microvascular invasion, and differentiation." (PMID 35715787, 2022). "AFP has been associated with the upregulation of proteins related to cellular infiltration and distant metastasis, promoting tumor growth and progression." (PMID 36684155, 2022). "Portal vein tumor thrombus (PVTT) (p = 0.03), the number of intrahepatic tumors (p = 0.01), and AFP level (p = 0.02) were independent risk factors for local tumor progression (LTP)." (PMID 36471084, 2022). "The following serum tumor markers, AFP, β-hCG and LDH, play important diagnostic roles, and higher levels correlate with an increased burden of disease and are used for risk assignment as well as for treatment assessment." (PMID 35204369, 2022). "Some studies have described that increased AFP levels can predict the risk of tumor relapse after surgical resection or response to loco-regional treatment and survival in HCC." (PMID 35158892, 2022). "Treatment-naïve tumors, treatment modality, AFP level, tumor size, and BCLC stage were associated with two-year DFS in the univariate analysis." (PMID 35053997, 2022). "AFP is an important tumor marker for HCC and has been confirmed to be associated with CK19 expression." (PMID 36741705, 2022). "Tumour diameter greater than three centimetres, multifocal tumour disease, vascular invasion, preoperative low albumin and increased alpha-fetoprotein (AFP) values were associated with significantly worse OS." (PMID 36233670, 2022). "The parameters included in point assigning were tumor number and size, alpha-fetoprotein, albumin, bilirubin, vascular invasion, cause, and response, as assessed by mRECIST criteria." (PMID 35330436, 2022). "Tumor size larger than 30 mm, beyond Milan criteria, AFP value pre-LT, and AFP SCORE progression were associated (i.e., p-value <0.10) with MVI in univariate analysis." (PMID 35401038, 2022). "They concluded that with four simple risk factors (AFP, tumor size, multiple tumors or satellite nodules, and microvascular invasion), it was possible to predict high-risk groups for early IHR." (PMID 35565210, 2022). "In this study, we identified only AFP levels and tumor number were associated with RFS probability in HCV-related HCC patients after thermal ablation combined with TACE." (PMID 36212462, 2022). "Univariable analyses indicated that the variables AFP, tumor size, grade, tumor number, and Stage AJCC were associated with a shorter RFS." (PMID 35352293, 2022). "It is essential to restrict the maximum eligible tumor burden in increasing AFP categories to keep the risk of HCC recurrence within acceptable limits." (PMID 35529597, 2022). "Higher CCT7 protein expression was associated with higher TNM staging (P = 0.043), serum AFP expression (P < 0.001), tumor differentiation (P = 0.010), vascular invasion (P = 0.029) and recurrence (P = 0.005) in HCC patients." (PMID 35073517, 2022).
tumor (continued). "Lower PDE2A expression was a protective factor in HCC and was negatively associated with serum AFP levels, tumor status, vascular invasion, histologic grade, and pathologic stage of HCC." (PMID 36611861, 2022). "Traditional tumor markers such as AFP, AFP-L3 are susceptible to other liver diseases and cannot analyze HCC for etiology, which has certain limitations." (PMID 35692794, 2022). "Serum AFP levels of > 400 ng/mL was significantly associated with a large tumor size, advanced tumor pathological stage, and high tumor recurrence (p < 0.001, p = 0.033, and p = 0.026, respectively)." (PMID 36117166, 2022). "Patients in HS high-risk group had elevated preoperative alpha-fetoprotein levels, poorer tumor differentiation and a higher proportion of microvascular invasion." (PMID 36059627, 2022). "In this study, we identified three adverse risk factors (periportal, tumor size, and AFP ≥ 400 ng/ml) that predict tumor progression after RFA in the univariate and multivariate analysis." (PMID 34983650, 2022). "Several studies reported that tumor size, vascular invasion, histological differentiation, tumor stage, serum AFP, etc., increased the risk for distant metastasis." (PMID 36127436, 2022). "Chi-squared analysis indicated that high SHC4 expression was notably associated with gender (P = 0.003), AFP level (P < 0.01), tumor encapsulation (P = 0.002), and tumor differentiation (P = 0.023)." (PMID 35033067, 2022). "Higher S100A9 levels are associated with higher AFP levels, pathological stages, and larger tumor sizes." (PMID 36041055, 2022). "High CPI values were associated with increased levels of alpha-fetoprotein (AFP) and advanced tumor stages." (PMID 36408192, 2022). "•The independent risk factors for HCC recurrence in our study were AFP >400 ng/mL, moderate/poor differentiated tumor, and microvascular invasion." (PMID 36268362, 2022). "As we know, alpha-fetoprotein (AFP) is a kind of diagnostic tumor marker that is commonly associated with LIHC." (PMID 35601740, 2022). "In a total of 845 HCC patients, the elevated expression of UBE2S was significantly associated with higher tumor grade, larger tumor volume, vascular invasion, higher serum AFP level, advanced TNM stage, recurrence, and poorer outcomes." (PMID 36262473, 2022). "In accordance with the multivariate analysis, tumor size, tumor number, alpha-fetoprotein (AFP), and histological grade were independently associated with MVI." (PMID 36684226, 2022). "Bispecific antibodies are designed to recognize and bind specific tumor-associated antigens (e.g. AFP, GPC3) and effector cell receptors (e.g. CD3, CD28) in order to initiate tumor cytotoxicity." (PMID 35433430, 2022). "Specifically, high expression levels of DDX56 were significantly associated with alpha-fetoprotein (AFP) level > 400 (P < 0.05), advanced tumor T classification (P < 0.05), and histologic grade (P < 0.05);." (PMID 36168636, 2022). "Alpha-fetoprotein also correlated well with Tumour Burden Score and remains a very important diagnostic and prognostic tool for patients with HCC." (PMID 35497085, 2022). "After univariable and multivariable regression analyses, two risk factors in the training subset, AFP and tumor size, were selected for clinical model construction." (PMID 35664790, 2022). "Other tumor types associated with elevated AFP include cholangiocarcinoma and hepatic lymphosarcoma." (PMID 36136704, 2022). "Clearly, it was found that risk score, tumor size, AFP, and CEA were remarkably correlated with OS of HCC patients (p < 0.05)." (PMID 35720008, 2022). "EXO1 expression levels in the HCC tissues were associated with the tumor grades, alpha-fetoprotein (AFP) levels, and the tumor stages." (PMID 35769911, 2022). "Regarding the mechanism underlying the relationship between AFP and tumor behaviors, several potential processes have been proposed." (PMID 35053580, 2022).
tumor (continued). "The both types of short sequences used as queries for sequence similarity search were derived from AFP, a major mammalian embryo-specific and tumor-associated protein." (PMID 36670957, 2022). "The results showed that sex, marriage, race, histological tumor grade, T stage, surgery, chemotherapy, AFP, and tumor size were independent risk factors for patient prognosis." (PMID 35296046, 2022). "In a single center in China, AFP level, ascites, and total bilirubin level were independent risk factors for poor short-term survival, whereas tumor differentiation and AFP level were associated with long-term survival." (PMID 36420403, 2022). "High AFP levels are known to be associated with tumor aggressiveness, poorly differentiated tumors, and mVI." (PMID 35529597, 2022). "We found that sex, marriage, race, histological tumor grade, T stage, surgery, chemotherapy, AFP, and tumor size were independent risk factors for patient prognosis." (PMID 35296046, 2022). "For N0M0 patients undergoing radical hepatectomy, an RWS found that older, Black, male patients, higher tumor stage, larger tumor, traditional radiotherapy and higher AFP levels were often associated with poor prognosis." (PMID 36358825, 2022). "The results showed that age, tumor size, clinicopathological stage, c-Met expression, and serum AFP level were correlated with 5-year survival risk (p < 0.05)." (PMID 35710379, 2022). "The best performance was observed when combining imaging features from the arterial and hepatobiliary phases of Gd-EOB-DTPA-enhanced MRI with the two clinical risk factors AFP and tumor size." (PMID 35664790, 2022). "In LT patients, a high pre-operative AFP level is associated with an increased risk of tumor recurrence after transplant and inversely correlates with OS." (PMID 35227234, 2022). "Other factors such as AFP level ≥400 μg/L, tumor diameter ≥2 cm, and tumor number ≥2 were independent risk factors for postoperative recurrence and long-term survival (P < 0.05)." (PMID 35795230, 2022). "Macrotrabecular massive HCC was associated with a high serum AFP level, large tumor size, and frequent LVI." (PMID 36117166, 2022). "In multivariate analysis, the recurrence time, tumor size and AFP > 400 ng/mL at the time of recurrence were associated with RTDS." (PMID 35585534, 2022). "In several investigations, epithelial CTCs were observed to be linked with AFP levels, the size of the tumor, and BCLC stage." (PMID 35884432, 2022). "The data showed that in the training cohort, CTC positivity was associated with AFP ≥ 400 μg/L, tumor number, and microvascular invasion (MVI) (P < 0.05)." (PMID 35795230, 2022). "Clinically, patients in the high-risk group exhibited more aggressive traits with high AFP level, poor tumor differentiation, vascular invasion, advanced cancer stages, and poor prognosis." (PMID 35193591, 2022). "In MC-out patients, the risk of tumor recurrence gradually increases with AFP values between 20 and 1,000 ng/ml at LT, thereby providing a risk stratification within defined criteria of tumor size and number." (PMID 35529597, 2022). "In males, AFP > 400, intraoperative blood loss, tumor diameter > 5 cm, satellite lesions, and macrovascular invasion were independent risk factors for RFS." (PMID 35313836, 2022). "Some well-known secreted tumor markers include AFP, cell surface-associated protein (MUC1 or CA15-3), gastrin-releasing peptide, and prostate-specific antigen (or KLK3)." (PMID 35719915, 2022). "Surrogate parameters like tumor size and number or serum alpha fetoprotein (AFP) levels are still in use for predicting the risk of mVI." (PMID 35529597, 2022). "Univariate analysis showed that HBsAg positivity, AFP level ≥400 ng/ml, liver capsule invasion, and tumor number ≥2 were risk factors for tumor recurrence after hepatectomy." (PMID 36420403, 2022). "The association between tumor size and AFP level is noteworthy because we found that the larger the tumor size, the higher the level of AFP." (PMID 35411218, 2022).